CTSB (cathepsin B)
Diseases named in the same sentence as CTSB in open-access papers (continued):
Sharing a sentence is not in itself a finding about the gene and the disease.
infection (continued). "The TLR4 signal activation also attenuated the CD4-independent vector infection by enhancing cathepsin B expression." (PMID 21541353, 2011). "C33A cells were as susceptible to the CD4-independent mNDK vector infection as TE671 cells, and have similar level of cathepsin B activity to TE671 cells." (PMID 21541353, 2011). "Infection with Mtb increased cytosolic cathepsin B activity compared to uninfected cells in a dose-dependent manner." (PMID 21483832, 2011). "TLR4 signal activation by the CD4-TLR4 attenuated the CD4-independent HIV-1 vector infection by enhancing cathepsin B expression, suggesting that cathepsin B functions as an innate immune factor resisting the CD4-independent HIV-1." (PMID 21541353, 2011). "MEFs deficient for either cathepsin B, cathepsin L, or wild type MEFs, i.e., cathepsin B and L positive, were infected with HPV16 reporter-virions and analyzed for infection levels after 48 hours." (PMID 19619315, 2009). "Our data showed that broad cysteine protease inhibitors and specific cathepsin B or L inhibitors were able to decrease infection, thus suggesting that cysteine proteases were in part mediating HPV16 infection in 293 cells." (PMID 19619315, 2009). "Alternative approaches, such as inhibition of the cysteine protease cathepsin B1 by K11777 early in the infection, have drastically decreased both worm and eggs burdens, delaying the egg-associated organ pathology." (PMID 19597543, 2009). "This is strongly supported by the positive identification of cathepsin B by affinity purification of proteins labeled during infection." (PMID 19744337, 2009). "HPV16 reporter-virions were treated with cathepsin B or cathepsin L protease for various amounts of time at 37°C, added to cells, and infections were analyzed by flow cytometry after 48 hours (for DsRED expression)." (PMID 19619315, 2009). "It is possible that HPV16 utilizes cathepsin B as a "backup" mechanism for furin in order to establish infection." (PMID 19619315, 2009). "Doxycycline induction of RNAi targeting cathepsin B led to parasite clearance from the bloodstream and prevent a lethal infection in the mice." (PMID 18820745, 2008). "Utilizing RNA interference that blocks the production of these proteins in the parasite, we show that elimination of parasite cathepsin B cures infection in mice." (PMID 18820745, 2008). "The increased exosomal protein quantity after infection was largely reduced by CTSB inhibitor." (PMID 41277866, 2026). "burnetii removes the lysosomal protease cathepsin B during infection of mammalian cells." (PMID 41467843, 2025). "Interestingly, we observed that GFP was cleaved from the fusion protein in an infection-dependent manner, however the relative abundance of the CTSB-GFP fusion protein (75 kDa) was unchanged during infection compared to uninfected cells." (PMID 40274809, 2025). "Moreover, cathepsin B was lost during icmS::Tn infection at increasing MOI, signifying that translocation of the responsible effector(s) is IcmS-independent." (PMID 40274809, 2025). "Given that CvpB modulates cathepsin B dynamics during infection, we assessed whether CvpB was also mediating the secretion of lysosomal proteins." (PMID 40274809, 2025). "To elucidate whether PIKfyve inhibition contributes to cathepsin B dynamics during infection, we utilised the PIKfyve inhibitor vacuolin-1." (PMID 40274809, 2025). "Interestingly, we observed secretion of a suite of lysosomal proteins, including cathepsin B, into the extracellular milieu during infection via a mechanism that involves the default secretory pathway." (PMID 40274809, 2025). "Two homologues of cathepsin B from black rockfish have been systematically characterized in this study, and the expression patterns have been deeply evaluated in multiple tissues of healthy fish and after infection." (PMID 40422803, 2025).
infection (continued). "However, infection of these cells with C. burnetii again led to cathepsin B removal, suggesting that decreased levels of proteolytically active cathepsin B during infection are not a consequence of the altered endosomal compartment." (PMID 40274809, 2025). "We therefore hypothesise that retention of cathepsin B during cvpB::Tn infection is a result of an altered CCV environment." (PMID 40274809, 2025). "This implies that while CvpB is involved in the intracellular loss of cathepsin B, this effector protein is not responsible for the global secretion of lysosomal content during infection." (PMID 40274809, 2025). "However, a single peptide was identified from the pro-domain of cathepsin B, and this peptide was significantly increased in abundance during infection." (PMID 40274809, 2025). "However, only infection with ESX-1-proficient M. marinum produced cathepsin B activity in the cytosolic compartment, suggesting that ESX-1-dependent permeabilization of the lysosomal membrane causes leakage of cathepsin B into the cytosol." (PMID 39087767, 2024). "For instance, CTSB and cathepsin S have been shown to contribute to apoptosis via caspase activation in Noroviruses and DENV infections, while highly pathogenic human CoVs, including SARS-CoV, MERS-CoV, and SARS-CoV-2, utilize cathepsin L to activate apoptosis and facilitate viral dissemination." (PMID 38354122, 2024). "There was greater cathepsin B protein expression in the CF cells after infection with MA." (PMID 39413095, 2024). "We plotted the R-Luc activity (infection efficiency) relative to the measured cell viability (F-Luc) and noted a significant downregulation of infection efficiency relative to cell viability for all three CTSB single guide RNAs and two of three CTSL single guide RNAs." (PMID 38319076, 2024). "Next, we investigated whether increased cathepsin B activity due to infection enhances cell death during infection." (PMID 37457695, 2023). "To find out whether the expression of the viral S2 protein activates CTSB and Abl2, we used qRT-PCR to analyze the relative expression in the rSczy3 infection, the S2 transfected group, and the mock groups." (PMID 37376546, 2023). "The naturally derived reoviruses uncoated less efficiently in L929 cells and were more dependent on extracellular proteolysis for productive infection compared to lab-adapted strains, which depend mainly on lysosomal cathepsin L for intracellular uncoating with a minor contribution by cathepsin B." (PMID 37747236, 2023). "To further understand the mechanisms underlying the activation of pyroptosis, we investigated whether cathepsin B influences the occurrence of pyroptosis during infection." (PMID 37457695, 2023). "In addition, we found that inhibition of p38, ERK, NF-κB, serine proteases and Cathepsin B resulted in significantly lower expression of pro-IL-1β compared to DMSO treated cells after CFT073 infection at MOI 1 for 4h." (PMID 34944029, 2021). "As macrophages constitutively express CD74 the presence of the p41 invariant chain might block the activity of cathepsin B/L contributing to the resistance of hMDM to the infection by SARS-CoV and SARS-CoV-2." (PMID 33912475, 2021). "Finally, to address the role of lysosomal cathepsin B in regulating the activation of NLRP3 inflammasome during ΔpknF mutant infection, release of cathepsin B was measured at 0, 2, 4, 6, 20 and 24 hpi." (PMID 34324582, 2021). "This indicates that cathepsin B activity reduces the susceptibility of target cells to CD4-independent infection while not affecting CD4-dependent infection." (PMID 34421929, 2021). "The implication was that the remaining infection occurred through the Cathepsin B/L pathway." (PMID 33290397, 2020). "Whether the CHIKV-pseudotyped MLV vector particles are internalized into target cells by endocytosis or by macropinocytosis, cathepsin B protease is undoubtedly important for the infection." (PMID 32635194, 2020).
infection (continued). "Furthermore, in situ analysis of CTSB activity was evaluated during BMDM infection and was enhanced in the presence of Mtb." (PMID 29977244, 2018). "However, HIV-infected MDM secreted significantly higher levels of cathepsin B than did uninfected MDM at 12 days post-infection, when virus production and cathepsin B mRNA levels peak (p<0.05)." (PMID 22693552, 2012). "However, intracellular cathepsin B expression remained constant throughout infection in cultured macrophages, suggesting increased secretion of the enzyme." (PMID 22693552, 2012). "A trend of increased cathepsin B activity was observed at days 6 and 9 post-infection." (PMID 22693552, 2012). "Our results also indicated that exploring various fusions of DNA vaccination strategies may be an effective approach to further enhance the potency cathepsin B against challenge infection in animal models." (PMID 22938392, 2012). "Because BcCVs show a marked delay in phagolysosomal fusion and retain a high pH for several hours post-infection, we speculate that cathepsin B plays at most a minimal role in NLRP3 inflammasome activation subsequent to B. cenocepacia infection." (PMID 22848580, 2012). "Overexpression of cathepsin B attenuated the CD4-independent vector infection in 293T cells." (PMID 21541353, 2011). "Previous studies had shown that low endosomal pH is required for infection and cell-cell fusion mediated by Ebola virus GP and that low pH is required for optimal functioning of cathepsin B and L, which are important to the initial step of Ebola virus entry into target cells." (PMID 21249196, 2011). "Compared to the 46.58% infection in the cathepsin B +/+ wild type MEFs (cath B +/+ with HPV16), cathepsin B deficient -/- MEFs were not susceptible to infection, yielding only 0.80% infection (cath B -/- with HPV16)." (PMID 19619315, 2009). "Because our data suggested that cathepsin B may play a role in the infection pathway of 293 cells, we were interested in determining if our observation was cell line specific." (PMID 19619315, 2009). "Affinity purification of activity-based protein profiling targets and identification by peptide mass fingerprinting showed that the cysteine protease cathepsin B was activated early in infection, establishing this protein as an upstream activator of the intrinsic apoptotic pathway." (PMID 19744337, 2009). "This study also found cathepsin B to be activated early in infection." (PMID 19744337, 2009). "The data suggested that cathepsin B protease is required for infection of HPV16 in MEFs." (PMID 19619315, 2009). "Notably, the activity of CTSB increased progressively within 14 days of infection." (PMID 41277866, 2026). "However, proteasome inhibition did not have any impact on the abundance of cathepsin B, demonstrating that the proteasome is not responsible for cathepsin B loss during infection." (PMID 40274809, 2025). "We next aimed to determine the cellular pathway behind cathepsin B loss during infection and queried whether the absence of intracellular cathepsin B was correlated with increased secretion of the protein into the extracellular space." (PMID 40274809, 2025). "At 24 h, cathepsin B was upregulated by infection with conidia, whereas both propagules resulted in a downregulation of cecropin and defensin A. At 48 h, blastospores and conidia increased the expression of defensin A suggesting this may be an essential AMP against EPF." (PMID 36650591, 2023). "In addition, we did not see any effect on cell death or ASC-speck formation when cells were treated with Bafilomycin A1 (BafA1) which inhibits lysosomal acidification by V-ATPase, or the pan-cathepsin inhibitor K777, during infection, despite efficient cathepsin B inhibition." (PMID 32385301, 2020).
infection (continued). "Therefore, we compared levels of cathepsin B secreted by HIV-infected MDM obtained from 7 different donors with productive infection (as demonstrated by increased levels of HIV-1 p24 antigen over time) to those secreted by MDM obtained from uninfected controls (data not shown)." (PMID 22693552, 2012). "Because cathepsin B protease, a natural ligand of cystatin C, was upregulated in HeLa cells, we speculated that the high levels of cathepsin B activities were inhibitory to the CD4-independent infection and that cystatin C enhanced the infection by impairing the excessive cathepsin B activity." (PMID 21541353, 2011). "To examine the involvement of cathepsin B in L. pneumophila-induced necrotic cell death, we assayed the cellular level of pro-cathepsin B. The level of pro-cathepsin B gradually diminished over time following infection, suggesting its processing into an active enzyme." (PMID 21092200, 2010). "Infection activates the NLRP3 inflammasome via ROS, cathepsin B, and potassium efflux, promoting IL-1β/IL-18 secretion and ASC oligomerization." (PMID 42245999, 2026). "We compensated for this by infecting at multiplicities of infection (MOI) up to 500X greater than wild-type and examining cathepsin B abundance at the population level with immunoblotting." (PMID 40274809, 2025). "Therefore, CtsB may act as a host defense factor, limiting infection of target cells by HIV-1." (PMID 41369389, 2025). "This gradual dispersal of CTSB and CTSD with infection time was also observed in NDV-infected A549 cells." (PMID 38354122, 2024). "Among the molecules screened, we found that cathepsin B significantly enhanced SARS-CoV-2 infection, while neutrophil elastase significantly inhibited infection, consistent with previous studies." (PMID 39286971, 2024). "We also found that cathepsin B activation is involved in the induction of pyroptosis and NLRP3 inflammasome formation during infection." (PMID 37457695, 2023). "The gene expression level and enzyme activity of cathepsin B (Cath B) in B. tabaci MED co-infected with ToCV and TYLCV increased compared with those under ToCV infection alone." (PMID 37007483, 2023). "We used the rescued strain rSczy3 to infect CEKs and performed qRT-PCR to evaluate the relative expression levels of CTSL, CTSB, Abl1, Abl2, IFITM3, ADAM17, TMPRSS2, NRP1, and CD74 at 12 and 24 h post-infection." (PMID 37376546, 2023). "After 30 min of infection with E. coli, the TG cells pretreated with the inhibitors dasatinib, filipin, and TAK242 had significantly reduced cathepsin B activity (P < 0.01)." (PMID 33966642, 2021). "Then, we analyzed the lysosome function by detecting the lysosome proteins cathepsin B (CTSB) and cathepsin D (CTSD) via western blotting, and found that CTSB and CTSD were increased after infection, which was almost abolished by Tas2r138 knockdown." (PMID 34083514, 2021). "The cathepsin B silencing decreased the relative infected cell numbers of the CHIKV-pseudotyped MLV vector, but the VSV-pseudotyped MLV vector infection was rather enhanced." (PMID 32635194, 2020). "We estimated thus that in Vero cells expressing TMPRSS2, infection proceeded ~65% of the time via the TMPRSS2 pathway and ~35% via the Cathepsin B/L pathway." (PMID 33290397, 2020). "Cathepsin B inhibitor and knockdown by an shRNA suppressed CHIKV-pseudotyped MLV vector infection both in 293T and TE671 cells." (PMID 32635194, 2020). "The exogenous expression of cathepsin B enhanced the infection by CHIKV-pseudotyped MLV vector in 293T and TE671 cells, but slightly reduced the VSV-pseudotyped MLV vector infection." (PMID 32635194, 2020). "Excessive ICP and infections also often accompany TBI and treatment with a cathepsin B inhibitor reduced ICP, improved clinical scores, and lowered CSF white blood cell counts in a brain meningitis animal model." (PMID 26388830, 2015).
infection (continued). "Cathepsin B intracellular activity in both HIV-infected and control uninfected samples remained unchanged throughout the infection." (PMID 22693552, 2012). "To determine the activity of intracellular cathepsin B in HIV-infected and uninfected samples, we isolated and cultured MDM from four additional female donors for in vitro infections with HIV-ADA." (PMID 22693552, 2012). "Because cathepsin B is activated by low pH in acidic endosomes, we further examined the potential roles of endosomes in the CD4-independent infection." (PMID 21541353, 2011). "However, because cathepsin B clearly had an inhibitory effect on the CD4-independent infection and because cathepsin B activity in 293T cells is extremely low, 293T cells could have another factor(s) suppressing cathepsin B activity that is not expressed in HeLa cells." (PMID 21541353, 2011). "When the cathepsin B-overexpressing 293T cells were treated with CA-074Me at 25 μM, the CD4-independent vector infection was enhanced, as in HeLa and TE671 cells." (PMID 21541353, 2011). "Our results are consistent with their conclusions that the intrinsic apoptotic pathway becomes activated in RAW264.7 cells following infection by MNV and that cathepsin B acts upstream of cytochrome C release from mitochondria in this process." (PMID 19744337, 2009). "Together, these data demonstrate that CvpB is necessary but not sufficient for cathepsin B removal during infection." (PMID 40274809, 2025). "Quantification of C. burnetii intracellular replication over 5 days of infection revealed that replication was lower in CTSB-GFP cells than cells expressing GFP alone at day 3 (mean difference 122.9 ± 28.96, p = 0.006) and day 5 (457.1 ± 123.5, p = 0.03) post infection." (PMID 40274809, 2025). "Infection with icmL::Tn at any MOI tested led to greater retention of cathepsin B than wild-type infection, indicating that T4SS activity is required for cathepsin B removal." (PMID 40274809, 2025). "Quantitation of cathepsin B signal intensity revealed that infection with cvpB::Tn did not lead to a significant reduction in cathepsin B compared to uninfected cells, contrary to the phenotype observed during infection with wild-type or the complement." (PMID 40274809, 2025). "While the role of cathepsin B in IIV6 remains unclear, baculoviral cathepsin L, along with chitinase, is known to contribute to larval tissue degradation and liquefaction during infection." (PMID 41305332, 2025). "Supporting this, examination of proteome Z-scores indicated an increase in the abundance of cathepsin proteases during infection, with the exceptions of cathepsin C (CTSC) which showed a small reduction, and cathepsin B (CTSB), which was dramatically decreased." (PMID 40274809, 2025). "In contrast, ECTV infection of BMDCs silenced for CtsB, L, or S did not affect cytokine production, maturation, or CD4+ T cell stimulation, indicating that modulation of DC function by ECTV occurs largely independently of cathepsins." (PMID 41369389, 2025). "The lack of cytosolic serpins in serpina3g-KO macrophages did not significantly affect the production of type I IFN in response to infection, and similar to the situation in IFNAR-KO macrophages, the production of cathepsin B was unaffected in serpina3g-KO cells." (PMID 39087767, 2024). "Unlike Delta infection, Omicron infection has been shown to result in an increased dependence on cathepsin B instead of on transmembrane serine protease 2 (TMPRSS2)." (PMID 38201428, 2024). "Through transcriptome analysis of B. tabaci MED that fed on co-infected plants from two viruses with different infection modes and a single infection, it was found that when ToCV and TYLCV were present at the same time, the cathepsin B gene of B. tabaci MED was significantly upregulated." (PMID 37007483, 2023).